IL6 (interleukin 6)
Diseases named in the same sentence as IL6 in open-access papers (continued):
Sharing a sentence is not in itself a finding about the gene and the disease.
tumor (continued). "PROTEIN-BOUND POLYSACCHARIDE K induces IL-1, IL-6, and IL-8 in peripheral mononuclear cells, as well as tumour necrosis factor and macrophage chemotactic factor at the tumour sites, thereby activating programmed cell death." (PMID 14997197, 2004). "Such tumour-produced molecules, including IL-4, IL-6, IL-10, CSF-1, TGFβ and prostaglandin E2 (PGE2), and TAM-produced factors such as IL-10 and PGE2, contribute to the general immunosuppression of the host as well as the antitumour activity of macrophages." (PMID 15164120, 2004). "In the cancer patients, there was a significant increase in both interleukin-6 and C-reactive protein concentration with increasing tumour grade." (PMID 15505624, 2004). "Our results indirectly support the earlier observations of Basolo and co-workers, who showed that a low tumour level of IL-6 correlated with a more aggressive phenotype." (PMID 14735187, 2004). "The combination of IL-6+IL-6sR was considerably more potent at simulating activity in proximal and tumour fibroblasts than PGE2, by 9.6– and 7.1-fold, respectively." (PMID 12592380, 2003). "As consistently observed in previous studies, the ability of PGE2 to stimulate aromatase activity in proximal and tumour fibroblasts (520 and 100%, respectively) was considerably lower than that achieved with IL-6+IL-6sR (960 and 710%, respectively)." (PMID 12592380, 2003). "The extent to which IL-6+IL-6sR-stimulated aromatase was also greater in proximal fibroblasts (20.8-fold) than in tumour fibroblasts (7.9-fold)." (PMID 12592380, 2003). "In contrast, serum interleukin-6 was highly elevated in the draining veins in agreement with expression of interleukin-6 in the cytoplasm of tumour cells." (PMID 12454774, 2002). "IL-6 is a pleiotropic cytokine secreted by a wide variety of cell types including lymphocytes, monocytes and tumour cells." (PMID 11986770, 2002). "We elaborate on an important role of tumour cell produced IL-6 in the enhanced platelet VEGF-A load of cancer patients explaining herewith the previously found correlation between serum IL-6, VEGF-A and the VEGF-A load in platelets." (PMID 12454774, 2002). "Tumour differentiation, hormone receptor status, stage at presentation, number of sites involved, presence of visceral disease, serum IL-6, plasma VEGF, serum fibrinogen were also prognostic parameters." (PMID 11875705, 2002). "In the present work we measured the circulating factors VEGF and IL-6 in veins draining the tumour in order to provide direct evidence of tumour secretion of these factors." (PMID 12454774, 2002). "We propose that interleukin-6 indirectly promotes tumour angiogenesis through its up-regulation of the vascular endothelial growth factor-A load in platelets." (PMID 12454774, 2002). "In order to find evidence for IL-6 and D-dimer secretion by metastatic cells we compared arterio-venous differences in the primary tumour of patients with metastasis (n=6)." (PMID 12454774, 2002). "Recent reports suggest that circulating IL-6 secreted from tumour cells plays an important role in cancer-induced cachexia." (PMID 10027341, 1999). "A phase II trial investigating the anti-tumour effects of recombinant human interleukin 6 (rhIL-6) in patients with metastatic renal cell cancer was carried out." (PMID 8611381, 1996). "Tumour necrosis factor (TNF) alpha, interleukin (IL) 1 and IL-6 are strongly induced by photodynamic treatment, supporting inflammatory action and immunological anti-tumour responses." (PMID 8679454, 1996). "In the present study, we examined the role of IL-1 production in three human tumour cell lines producing granulocyte (G)-CSF, IL-1 and IL-6." (PMID 1373292, 1992).
tumor (continued). "The IL‐6‐type cytokines have multiple roles in tumor progression." (PMID 40968783, 2026). "In addition, Wnt/β‐catenin activation, which is frequently detected in MASLD‐related HCC, acts in concert with JAK/STAT signalling induced by pro‐inflammatory cytokines such as IL‐6 to sustain tumour growth and survival." (PMID 41071622, 2026). "Notably, several soluble factors associated with NET induction, including CXCL2, CXCL8, and IL‐6, were markedly upregulated in PUS7‐overexpressing tumour cells compared with controls." (PMID 41496500, 2026). "Mechanistically, hypoxia acts through tumor-fibroblast crosstalk to increase IL-6 expression in fibroblasts; in turn, fibroblast-derived IL-6 induces expression of arginase 1 (ARG1), a key mediator of immunosuppression, in macrophages via activation of the JAK/STAT signaling pathway." (PMID 42041553, 2026). "IL-6 is described as an important cytokine in tumor initiation and progression." (PMID 41596451, 2026). "Our findings reveal that tumor M-MDSCs upregulate 6PGD expression via IL-6/STAT3 signaling." (PMID 41535266, 2026). "Additionally cancer-associated fibroblasts (CAFs) further enhance metastatic potential by recruiting monocytes through IL-8/CXCR2 signaling and promoting M2 polarization through IL-6-mediated VCAM-1 upregulation in tumor cells." (PMID 41438574, 2026). "Blockade of P2X7R by AZ10606120 appears to activate a pro-tumor IL-6/STAT3 axis." (PMID 41896344, 2026). "Treatment with anti-IL-6 antibody reduced pain but had modest efficacy in tumor control." (PMID 41758723, 2026). "However, autophagy in CAFs promotes tumor development via providing nutrients (L-lactate, ketone bodies), cytokines (IL-1β, IL-6, IL-8), CXCL12, and α-SMA in advanced stages of tumorigenesis." (PMID 41328341, 2026). "Just as observed in other cancer types, such as pancreatic ductal adenocarcinoma, where “inflammatory” CAFs(iCAFs) strongly express IL6 and other cytokines and may promote tumor growth and drug resistance." (PMID 41601649, 2026). "Developmental pathways, including hedgehog, Notch, IL6/JAK/STAT3, and TGFβ signaling, along with hallmarks linked to tumor progression, stemness capacity, and metastasis (e.g., angiogenesis and EMT), displayed a significant positive association with WNTHigh populations." (PMID 41117706, 2026). "The OC cells secrete the same cytokines as epithelial cells such as IL-6, IL-1 and M-CSF, while normally secreted cytokines are recruited into the dysregulated autocrine cycle that drives tumor progression and induce the regulation of immunosuppressive bias by inflammatory factors in the peritoneum." (PMID 41601649, 2026). "Additionally, IL‐6 promotes tumor cell proliferation, survival, and angiogenesis, as well as evasion of immune surveillance to build a favorable environment for tumorigenesis." (PMID 40968783, 2026). "Notably, Nrf2 protein expression in tumor tissues was downregulated, while intratumoral IL-6 levels were also decreased." (PMID 42193203, 2026). "Therefore, to investigate the activation of endogenous immune responses, we first checked for the infiltration of embryo macrophages in the tumor and the endogenous IL-6 expression at the tumor site." (PMID 41596451, 2026). "The observations for both agents were correlated, and an evident increase in MMD (the macrophage-representing marker) expression was found in the group treated twice with CD19 CAR-T cells, with a significant upregulation of IL-6 at the tumor site in this group." (PMID 41596451, 2026). "Moreover, tumor cell stemness characteristics and inflammatory cytokines (e.g., TNFα, IL-6) promote upregulation of adhesion molecules on tumor cells, facilitating the formation of CTC clusters in peripheral blood." (PMID 40547026, 2025). "Targeting IL-6 therapeutically may improve treatment results and increase tumour sensitivity to radiation." (PMID 40724564, 2025).
tumor (continued). "At this time, immune dysregulation may occur, leading to a cytokine storm The massive release of cytokines such as IFN-γ, TNF-α, and IL-6 not only attacks tumor cells but also indirectly damages skeletal muscle cells." (PMID 40242775, 2025). "Regarding previously published work attesting the central roles of IL-6 and TNFα in TGCTs as well as our own results implicating these cytokines in tumor–immune interactions, we wondered about their specific relevance for the effect of the cytokine milieu on the tumor cells themselves." (PMID 40649953, 2025). "Beyond their interactions with T‐cells and fibroblasts, SPP1+ TAMs expressing angiogenic, matrix remodelling, and immunosuppressive markers like Nlrp3, Tnf, Vegfa, and Arg1, also engage in cross‐talk with enteric glial cells via IL1R/IL6 signalling, further influencing tumour behaviour." (PMID 40395129, 2025). "Further suppressing anti-tumor immune responses, VIRMA also controls the m6A modification levels of chemokines and inflammatory cytokines (like CXCL1 and IL-6), which encourages the growth of myeloid-derived suppressor cells (MDSCs) and regulatory T cells (Tregs) in the tumor microenvironment." (PMID 39911396, 2025). "CRP, which is produced by hepatocytes in response to IL-6 stimulation, is a cost-effective and widely available marker of inflammation that may also contribute to an immunosuppressive tumour microenvironment by directly impairing T-cell function." (PMID 40091005, 2025). "Similarly, CRIP2 inhibits tumor progression and angiogenesis by inhibiting NF-κB-mediated transcription of pro-angiogenic cytokines IL-6, IL-8, and vascular endothelial growth factor, providing important evidence that CRIP2 acts as a tumor suppressor." (PMID 40118853, 2025). "Therefore, while a higher IL-6 concentration increased the plasma concentration of osimertinib, IL-6 is expected to contribute to drug resistance and tumor progression during long-term EGFR-TKI therapy." (PMID 40156608, 2025). "Within tumors, IL-6 is known to stimulate tumor growth, survival, angiogenesis, and evasion of immune detection via IL-6/STAT3 signaling, as well as to enhance and propagate oncogenic signals within the TME, thereby promoting tumorigenesis, invasion, and metastasis." (PMID 39652104, 2025). "There is evidence that cannabinoids can decrease the production of IL-6 and prevent tumor growth." (PMID 40008130, 2025). "Similarly, TAM-derived IL-6 can facilitate PDPK1-mediated glycolysis in GBM cells to promote tumor growth." (PMID 40626360, 2025). "In particular, interleukin 6 expression has been associated with worse outcomes in patients with NSCLC treated with EGFR-TKIs, which may induce tumor refractoriness to EGFR-TKIs via JAK–STAT3 signaling activation or suppression of anti-tumor immune responses." (PMID 40136696, 2025). "As a result, IL-6 plays a role in initiating and advancing the growth of tumor cells." (PMID 39802656, 2025). "Elevated IL-6 levels in spheroids within the co-culture models, especially in the presence of macrophages, suggest that TAMs may enhance IL-6 secretion by tumour cells to drive tumour progression." (PMID 40420192, 2025). "Interestingly, the interleukin (IL)-6/Janus kinase (JAK)/STAT3 pathway was reported to contribute to tumor formation and progression in HNSCC by inducing the EMT." (PMID 40113769, 2025). "In MM, visfatin promotes tumor progression by upregulating IL-6 production, which may be a novel therapeutic target for the treatment of MM patients." (PMID 40392374, 2025). "Although the extracted factors explain 36.4% of the total variance, the results suggest that additional inflammatory markers, such as C-reactive protein or interleukin-6, might refine predictive models for tumor aggressiveness." (PMID 41010971, 2025). "IL-6 activates the IL-6–JAK–STAT3 pathway to promote tumor growth." (PMID 41246358, 2025).
tumor (continued). "Interestingly, a recent study showed that CIN triggers the IL-6/STAT3 signaling pathway located downstream of cGAS-STING, and the blockage of IL-6 signaling impairs tumor growth in a TNBC model with high CIN." (PMID 40227811, 2025). "The inflammatory process in GBM is driven by complex interactions between tumor cells and the tumor microenvironment, which involve changes in the concentration and activity of numerous cytokines and chemokines, including IL-6, IL-1β, and tumor necrosis factor α (TNF-α)." (PMID 40497976, 2025). "IL-6 is a cytokine abundantly expressed in the tumor microenvironment of various tumor types." (PMID 40281902, 2025). "For instance, studies in mouse models demonstrate that voluntary wheel running can increase NK cell infiltration into tumors and impede tumor growth, partly mediated by exercise-induced epinephrine release which primes NK cells via IL-6 signaling from other immune cells." (PMID 40900783, 2025). "Moreover, IL-6 is a cytokine that is abundantly present in the tumor microenvironment of various tumor types, including HNSCC." (PMID 41382246, 2025). "Detection of IL-6 levels in serum indicated that CaCO3@CM-OA treatment could significantly activate the inflammatory response in vivo, which aids in inhibiting tumor progression." (PMID 41377584, 2025). "Numerous studies have revealed that IL-6 induces an immunosuppressive tumor microenvironment." (PMID 39652104, 2025). "Similarly, PI3K/AKT/mTOR activation, which promotes tumor cell survival during chemotherapy, concurrently upregulates immunosuppressive cytokines such as IL-6, thereby fostering a hostile tumor microenvironment (TIME) to T-cell activity." (PMID 40650040, 2025). "Moreover, NF‐κB activity‐induced expression of the pro‐inflammatory cytokines IL‐1β, IL‐6 and TNFα were also elevated in the hippocampus of these tumour‐bearing mice." (PMID 40172096, 2025). "In favor of this, preclinical models involving inhibition of CCL2, NOS2, and LCN2 pathways have shown anti-tumor effects and may be explored to improve IL6 inhibitory strategies after PD-L1 treatment failure." (PMID 39663510, 2025). "This phenomenon correlated with the tumor grade and the level of interleukin-6 (IL-6)." (PMID 41440954, 2025). "Blocking IL-6 and its downstream signaling pathway could potentially reverse this highly suppressed tumor immune microenvironment." (PMID 40433391, 2025). "The interplay between sphingosine and IL-6 may contribute to tumor progression and cancer-related inflammation; however, the direct relationship between sphingosine metabolites and CYFRA 21-1 remains unclear." (PMID 41007708, 2025). "Based on the IPA of differentially expressed genes, we discovered activity changes of several pathways significantly associated with tumor behavior were activated over the course of surgery (FDR <5%), including IL-6, IL-8, HMGB1, HIF1α, IL-1, TGFβ, and TNFα signaling." (PMID 40331601, 2025). "Principally, TAMs promote tumor cell invasion and dissemination, and through their ability to release cytokines and factors that support growth and ECM-shaping (MMP-2, MMP-9), milk fat globule-EGF factor 8 (MFGE8), IL-6 are correlated with tumor progression and metastasis." (PMID 39981232, 2025). "We will also delve into the molecular and cellular mechanisms by which IL6 drives the pathogenesis of OC, including its influence on determining whether the cancer adopts a “hot” or “cold” tumor profile." (PMID 40427188, 2025). "Moreover, many pro-tumor actions can be supported by stimulation of IL-6 trans signaling, which also has the ability to boost adaptive immunity against tumors." (PMID 39996081, 2025). "Additionally, increased inflammatory factors such as TNF-α and IL-6 can alter the local immune microenvironment of the thyroid, inhibiting immune cells from recognizing and attacking tumor cells, making it easier for tumor cells to develop and progress." (PMID 40430234, 2025).
tumor (continued). "In prognostic assessment, longitudinal monitoring of the glutathione redox status (GSH/GSSG ratio), lactate levels, and IL-6 concentrations allows for quantitative characterization of spatiotemporally dynamic tumor redox stress and inflammatory microenvironments." (PMID 40563367, 2025). "In addition, cigarette smoke promotes a proinflammatory tumor microenvironment by stimulating the production of cytokines such as interleukin 6 (IL-6) and interleukin 8 (IL-8), both of which are involved in tumor progression, angiogenesis, and immune evasion." (PMID 41479792, 2025). "Both malignancies may exploit similar cytokine environments, particularly interleukin-6, which supports tumor proliferation and survival." (PMID 41346886, 2025). "The observed effect may be mediated by IL‐6, whose production contributes to ASCs pro‐tumor properties." (PMID 39763022, 2025). "We hypothesize that a "cytokine storm" involving tumor-derived G-CSF, granulocyte-macrophage colony-stimulating factor (GM-CSF), IL-5, and IL-6 was responsible for this presentation." (PMID 41431550, 2025). "Several other interleukins, such as IL-6, IL-10, IL-12, and IL-17, have been implicated in the pathogenesis of HPV infection and cervical cancer which may play important roles in the tumor microenvironment." (PMID 41408300, 2025). "This amplified inflammation may promote the survival and proliferation of microscopic tumor foci through IL-6/STAT3 activation, leading to rapid polyp development." (PMID 40650003, 2025). "In colon cancer, IL-4 and IL-6 promote tumor growth and metastasis." (PMID 40307509, 2025). "M2d macrophages, a subtype driven by IL-6 and adenosine, often referred to as tumor-supportive macrophages, are distinguished by their pro-angiogenic and cancer-fostering functions, aiding in new blood vessel formation and shaping the tumor microenvironment." (PMID 41154774, 2025). "Anti-IL-6R treatment could be investigated in these tumors as well, noting that anti-IL-6 was successfully used for this purpose in advanced renal cell carcinoma with documented IL-6 production by tumor cells." (PMID 39754984, 2025). "Tumor metastasis is significantly influenced by the epithelial-mesenchymal transition (EMT), Regarding the mechanism underlying PCa’s bone metastasis, one idea holds that IL-6 controls EMT and the cancer cells’ homing to the bone." (PMID 41142623, 2025). "Similar to IL-6, IL-17 exerts immune-suppressive effects during later stages of tumor development." (PMID 41376623, 2025). "For instance, IL-6 promotes tumor cell proliferation and angiogenesis; IL-10 exerts immunosuppressive effects that favor viral persistence; IL-12 enhances Th1-mediated antitumor immunity; and IL-17 is involved in chronic inflammation and tumor promotion." (PMID 41408300, 2025). "Based on this, we hypothesise that blocking IL‐11 and IL‐6 may have synergic outcomes and improve the anti‐tumour benefit of drugs." (PMID 40673604, 2025). "This may be related to the increased release of cytokines such as IL-10 and IL-6 in tumor microenvironment that can promote BTLA expression after PD-1/PD-L1 blockade." (PMID 40463377, 2025). "Specifically, the focus was placed on the immunomodulators and tumor promotors IL-6 and IDO1." (PMID 40699630, 2025). "TAFs in GCTs secrete factors like VEGF and IL-6 that promote tumor proliferation and metastasis." (PMID 40260236, 2025). "We propose that, under circumstances of vaccine-induced tumor cell destruction, IL-6 might have beneficial effects on the antitumor immune response." (PMID 39653766, 2025). "Previous studies have revealed that tumor cells can produce and release some inflammatory mediators, such as tumor necrosis factor-alpha and interleukin-6, which may inhibit the synthesis of albumin in the liver, potentially resulting in hypoproteinemia." (PMID 40265018, 2025).